RN7SL127P (RNA, 7SL, cytoplasmic 127, pseudogene)
Gene: Miscellaneous RNA gene on chromosome 4 (78,898,855 to 78,899,154, forward strand). Ensembl gene ENSG00000242175.
Homologues: Orthologues: chimpanzee Metazoa_SRP (98% identical), macaque Metazoa_SRP (83% identical). Paralogues in human: RN7SL1 (86% identical), RN7SL2 (86% identical), RN7SL3 (84% identical), RN7SL220P (84% identical), RN7SL493P (83% identical), RN7SL543P (82% identical), RN7SL672P (82% identical), RN7SL769P (82% identical), RN7SL566P (82% identical), RN7SL712P (82% identical), RN7SL788P (82% identical), RN7SL122P (82% identical), and 702 more.